KRT42P (keratin 42, pseudogene)
Gene: Transcribed unprocessed pseudogene on chromosome 17 (41,626,536 to 41,634,106, reverse strand). Ensembl gene ENSG00000214514.
Diseases named in the same sentence as KRT42P in open-access papers:
KRT42P is named in the same sentence as 1 disease in open-access papers, as found by Europe PMC text mining. Sharing a sentence is not in itself a finding about the gene and the disease. The quoted sentences say what the papers report.
cervical cancer (1 paper, 2023). A primary or metastatic malignant neoplasm involving the cervix. "On the other hand, high SULTIEI, RAB3C, CXCR3, PROX2, and KRT42P expression was associated with a better prognosis in cervical cancer." (PMID 37350944, 2023).